OPA3 (outer mitochondrial membrane lipid metabolism regulator OPA3)
Diseases named in the same sentence as OPA3 in open-access papers (continued):
Sharing a sentence is not in itself a finding about the gene and the disease.
COVID-19 (1 paper, 2025). A disease caused by infection with severe acute respiratory syndrome coronavirus 2. "However, OPA3 was down-regulated in the COVID-19 dataset and up-regulated in the MDD dataset." (PMID 40918512, 2025). "EMILIN3, OPA3, and TFCP2 are likely to be potential shared hub genes in both COVID-19 and depression." (PMID 40918512, 2025). "We used LASSO and RF methods to identify EMILIN3, OPA3, and TFCP2, as potential hub genes for both COVID-19 and MDD." (PMID 40918512, 2025). "Furthermore, when comparing COVID-19- and MDD-related hub genes, we found that three genes, i.e., TFCP2, OPA3, and EMILIN3, overlapped." (PMID 40918512, 2025). "Furthermore, OPA3 and TFCP2 are found in the DEGs expressed in peripheral blood neutrophils of COVID-19 patients." (PMID 40918512, 2025).
Cutis marmorata (1 paper, 2017). A reticular discoloration of the skin with cyanotic (reddish-blue appearing) areas surrounding pale central areas due to dilation of capillary blood vessels and stagnation of blood within the vessels. "By age 23 yr, she had cutis marmorata in her extremities, a novel phenotype for OPA3 mutations, suggesting some degree of vasomotor instability." (PMID 28050599, 2017).
depression (1 paper, 2025). "Furthermore, in the GSE101521 dataset, OPA3 and TFCP2 genes, but not EMILIN3, were found in the HP–depression enrichment pathway." (PMID 40918512, 2025).
Hepatic steatosis (1 paper, 2024). Steatosis is a term used to denote lipid accumulation within hepatocytes. "The upregulated mitochondrial protein OPA3 is a crucial regulator of mitochondrial function, whereas the expression levels of ACSL1 and MPC1 are directly correlated with hepatic steatosis." (PMID 39280921, 2024).
hepatocellular carcinoma (1 paper, 2024). A malignant tumor that arises from hepatocytes. "In hepatocellular carcinoma (HCC), OPA3 was markedly upregulated and associated with unfavorable prognosis." (PMID 38911373, 2024).
pancreatic ductal adenocarcinoma (1 paper, 2019). An infiltrating adenocarcinoma that arises from the epithelial cells of the pancreas. "Importantly, immunohistochemical staining revealed that OPA3 protein was highly expressed in clinical tumor specimens of pancreatic ductal adenocarcinoma (PDAC) as compared to human normal pancreatic tissues." (PMID 31881642, 2019).
prostate carcinoma (1 paper, 2022). A carcinoma that arises from epithelial cells of the prostate gland. "Whether inhibition of the key player OPA3 could serve as a diagnostic basis or therapeutic target for prostate cancer and could more comprehensively inhibit the progression of the tumor microenvironment." (PMID 35507809, 2022).
Wolfram syndrome (1 paper, 2014). Wolfram syndrome (WS) also known as DIDMOAD, is a neurodegenerative disorder characterized by type I diabetes mellitus (DM), diabetes insipidus (DI), sensorineural deafness (D), bilateral optical atrophy (OA) and neurological signs. "This differential diagnosis includes e.g. OPA3/Type III methylglutaconic aciduria (MIM 606580), OPA1 (MIM 605290) or Wolfram Syndrome (MIM 606201)." (PMID 24528855, 2014).
cancer (3 papers, 2019 to 2024). A tumor composed of atypical neoplastic, often pleomorphic cells that invade other tissues. "We then used the cBioPortal database to evaluate the mutation and frequency of OPA3 in OV tissues based on data from the Pan-Cancer Atlas database of OV patients obtained from TCGA." (PMID 35507809, 2022). "We found that 3% of OPA3 genes were mutated in various cancers." (PMID 35507809, 2022). "As such, OPA3 could be a potential target to kill cancer cells with K-ras mutations." (PMID 31881642, 2019). "There are few studies related to OPA3 and various cancers, and few studies have been conducted on this topic, it is an issue worth exploring in depth." (PMID 35507809, 2022). "To evaluate the role of OPA3 in K-ras-driven cancer cells, we first used shRNA strategy to construct a stable OPA3-knockdown cell line from Panc-1 cells, a human pancreatic cell line harboring K-rasG12D mutation." (PMID 31881642, 2019). "Currently there is very limited information on the regulation of Opa3 expression and its biological function in cancer cells." (PMID 31881642, 2019). "Our study suggested that in K-ras-driven cancer cells, OPA3 seems to mainly affect mitochondrial energy metabolism, and its impact on mitochondrial morphology appears minimal." (PMID 31881642, 2019). "The mechanism by which K-ras regulates OPA3 expression and its potential role in mitochondrial fission in cancer cells are other important areas for future study." (PMID 31881642, 2019). "This study observed a high level of differential OPA3 gene amplification in pan-cancer." (PMID 35507809, 2022). "Since metabolic changes might control signals that regulate basic cellular processes such as cell proliferation, we then tested if OPA3 might play a role in cancer cell proliferation, using both colony formation assay and direct cell counting." (PMID 31881642, 2019). "Currently there is very little information on the biological function of OPA3 in cancer cells." (PMID 31881642, 2019). "As such, OPA3 could be a potential target to kill K-ras-driven cancer cells." (PMID 31881642, 2019). "The main role of OPA3 appears to promote mitochondrial energy metabolism, and its up-regulation in K-ras-driven cancer is likely a mechanism to offset the negative impact of K-ras on mitochondria so that cellular energy homeostasis can be maintained." (PMID 31881642, 2019). "OPA3 may promote cellular energy metabolism, and its upregulation in K-ras-driven cancers may be a mechanism to counteract the negative effects of K-ras on mitochondria to maintain energy homeostasis." (PMID 35507809, 2022). "Our study suggests that OPA3 may promote cellular energy metabolism and its up-regulation in K-ras-driven cancer is likely a mechanism to offset the negative impact of K-ras on mitochondria to maintain energy homeostasis." (PMID 31881642, 2019).
tumor (3 papers, 2019 to 2024). "Limited research has been conducted on the role of OPA3 in tumor progression and the tumor microenvironment." (PMID 38911373, 2024). "It is worth noting that in normal pancreas OPA3 appeared mainly in the acinar cells, whereas in PDAC tissues OPA3 was highly expressed in the tumor cells." (PMID 31881642, 2019). "We examined the genetic alterations of OPA3 in various tumor types in the TCGA dataset." (PMID 35507809, 2022).
peripheral neuropathy (2 papers, 2017 to 2019). A disorder affecting the peripheral nervous system. "Symptoms or signs suggestive of peripheral neuropathy (PN) have been described to date in 4 individuals with dominant OPA3 mutations, although it was confirmed by nerve conduction studies (NCSs) in only one of them." (PMID 31119193, 2019).
metabolic disorders (1 paper, 2023). "Certain patients may harbor inherited metabolic disorders (e.g., OPA3 deficiency,) despite initially unremarkable biochemical testing." (PMID 37810989, 2023).
OPA3 also shares sentences with these, for which no sentence is quoted: Behr syndrome (2 papers); glaucoma (2); lipodystrophy (2); neuropathy (2); aniridia (1); autonomic neuropathy (1); axonal neuropathy (1); Best vitelliform macular dystrophy (1); beta-ketothiolase deficiency (1); breast carcinoma (1); Chorea (1); Cognitive impairment (1); diabetes mellitus (1); dihydrolipoamide dehydrogenase deficiency (1); dilated cardiomyopathy (1); exudative vitreoretinopathy (1); Familial exudative vitreoretinopathy (1); female reproductive cancers (1); glutaric aciduria type 1 (1); hearing loss (1); hereditary ceruloplasmin deficiency (1); hypertrophic cardiomyopathy (1); Leigh syndrome (1); Lesch-Nyhan syndrome (1); metachromatic leukodystrophy (1); movement disorder (1); multiple carboxylase deficiency (1); neuronal ceroid lipofuscinosis (1); neurosensory deafness (1); optic atrophy plus syndrome (1).
A further 6 diseases each share a sentence with OPA3 in 1 paper.